TF (transferrin)
Diseases named in the same sentence as TF in open-access papers (continued):
Sharing a sentence is not in itself a finding about the gene and the disease.
lymphoma (8 papers, 1983 to 2025). A malignant (clonal) proliferation of B- lymphocytes or T- lymphocytes which involves the lymph nodes, bone marrow and/or extranodal sites. "Similarly, the same results were also observed in lymphoma models, where transferrin overexpression significantly promoted primary tumor growth and metastasis, while transferrin knockdown inhibited primary tumor growth and metastasis." (PMID 39810853, 2025). "SOX11 is a TF with important roles in brain development that is strongly upregulated in lymphoma and malignant glioma, where it may affect tumorigenesis." (PMID 21226949, 2011). "Up to now, as an antihuman TFR1 antibody, JST-TFR09 has a strong affinity with TFR1 in human lymphoma cells and can inhibit iron uptake by interfering with the binding of TFR1 and TF." (PMID 36082181, 2022). "Similarly, variants within or in the neighborhood of TF genes may lead to aberrant TF expression and, in turn, gene dysregulation of almost all known cellular processes related to tumorigenesis, which could explain the widespread gene expression dysregulation observed in lymphoma." (PMID 38144469, 2023).
mastitis (8 papers, 2014 to 2022). Inflammation of breast tissue during lactation or postpartum due to an obstructed duct or infection. "The present study was carried out to study polymorphisms in the bovine transferrin gene in cows (with subclinical mastitis and healthy)." (PMID 35327090, 2022). "The Serotransferrin (TF) gene is reported as a major regulator of a set of genes that are responsible for the resistance/susceptibility of mastitis." (PMID 34222390, 2021). "This study investigated single-nucleotide polymorphisms (SNPs) in the bovine transferrin gene in the local cattle population and whether they were associated with either tolerance of or susceptibility to subclinical mastitis." (PMID 35327090, 2022). "In cattle, TF has been shown to be highly polymorphic and a study in Chinese native cattle indicated that TF polymorphisms are associated with protein yield, 305-day milk yield and mastitis susceptibility." (PMID 27716033, 2016). "During mastitis, as the tissue permeability is increased, transferrin passes from blood to milk; henceforth, the total iron binding capacity of milk is increased." (PMID 35327090, 2022). "Animals previously diagnosed with mastitis had higher concentration of transferrin in milk as compared to healthy animals." (PMID 35327090, 2022). "Several studies have reported polymorphism in the transferrin gene in dairy animals with mastitis, but no detailed information on in silico tools is available for identification and verification." (PMID 35327090, 2022). "A study using proteomics in bovine milk from mastitis cows, identified proteins involved in the immune response, including lactoferrin, transferrin, fibrinogen, apolipoprotein A1, glycosylation-dependent cell adhesion molecule-1, peptidoglycan recognition proteins, as well as cathelicidin-1." (PMID 36356101, 2022). "In addition, they showed that TF mRNA expression was higher in mastitis affected in comparison with unaffected mammary tissue." (PMID 27716033, 2016). "Since, co-expressed genes are likely to be functionally related and regulated by the same TF, the other highly connected genes in the blue module might be ideal candidates to better understand molecular mechanisms behind mastitis." (PMID 32754201, 2020). "In contrast to rodents, pigs, and rabbits, which synthesise TF in the MGs at higher concentrations, TF in the milk of dairy ruminants is not synthesised in the udder and instead comes from blood serum, from transcytosis in the normal gland, and through exudation of plasma during mastitis." (PMID 26464939, 2014). "Proteins that stand out as logical candidates for further analyses include various APPs and vascular-derived proteins such as C3, C4, TF, ALB, TTR, FGA, and ITIH4 in mastitis whey of E. coli infected cows by 2-DE and label-free methods, respectively." (PMID 36335251, 2022).
osteoarthritis (8 papers, 2014 to 2024). A noninflammatory degenerative joint disease occurring chiefly in older persons, characterized by degeneration of the articular cartilage, hypertrophy of bone at the margins and changes in the synovial membrane. "No greater prevalence of C282Y homozygosity mutation or elevated serum ferritin or transferrin saturation levels was found in the study cohort with severe osteoarthritis of the hip than in controls from the general population." (PMID 30427934, 2018). "Eleven metabolites were found to have a causal association with an increased risk of osteoarthritis, including isovaleryl carnitine, taurocholate, kynurenine, acetaminophen 4-sulfate, homocysteine, serum iron, transferrin saturation, insulin-like growth factor-1, serum copper, and serum zinc." (PMID 39172202, 2024). "Using the top 50 TF regulons attentions to perform the unsupervised pseudotime trajectory analysis, we show the changes of chondrocytes types upon the onset of osteoarthritis (OA)." (PMID 36641532, 2023). "On the other hand, 10 metabolites were associated with a reduced risk of osteoarthritis, such as 1-linolenoylglycerophosphorylcholine, arginine, alanine (Ala), omega-3 fatty acids, omega-6 fatty acids, LDL cholesterol, transferrin, folate, vitamin B12, and serum calcium." (PMID 39172202, 2024). "A previous MR study on iron status and osteoarthritis demonstrated a positive correlation between TSAT and osteoarthritis, while transferrin exhibited a negative correlation." (PMID 39345879, 2024).
psoriasis (8 papers, 2020 to 2024). An autoimmune condition characterized by red, well-delineated plaques with silvery scales that are usually on the extensor surfaces and scalp. "Intradermal injection of the ferroptosis inducer RSL3 in psoriasis-like mice significantly promoted and aggravated the development of psoriasis-like dermatitis, and the level of serum transferrin was also increased in PV samples." (PMID 36829869, 2023). "FOSL1 was identified as the TF encoding gene of psoriasis, and the enhanced FOSL1 expression was significantly correlated with high psoriasis area and severity index." (PMID 35774389, 2022). "The levels of trace elements and acute phase proteins (Cu, Fe, transferrin, ceruloplasmin), although significantly altered in patients with psoriasis, do not seem to correlate with the severity or duration of the disease." (PMID 35204165, 2022). "The role of low iron concentrations in psoriasis is indicated by changes in other iron-related laboratory parameters such as a decrease in the transferrin iron saturation index, hepecidin, and an increase in the soluble receptor, which for transferrin indicates a negative iron balance in the body." (PMID 38612631, 2024).
sarcopenia (8 papers, 2020 to 2024). Progressive decline in muscle mass due to aging which results in decreased functional capacity of muscles. "Serum iron, TIBC, and transferrin levels decreased significantly in the sarcopenia group (p < 0.05), and were negatively associated with handgrip strength, relative skeletal muscle index, and multiple test performances (p < 0.05)." (PMID 38719903, 2024). "In univariate logistic regression analysis, sex, age, BMI, albumin, hemoglobin, transferrin, serum iron, TIBC, and TSAT were significantly associated with the risk of sarcopenia." (PMID 38719903, 2024). "In clinical practice, iron status is indicated by several markers, including serum ferritin, transferrin, total iron binding capacity (TIBC), and transferrin saturation (TSAT) levels, which are much less frequently included in sarcopenia studies." (PMID 38719903, 2024). "In contrast, transferrin, TIBC, and serum iron levels were significantly lower in patients with sarcopenia." (PMID 38719903, 2024). "The laboratory results showed that patients without sarcopenia diagnosis had a transferrin value higher than those with sarcopenia diagnosis (p = 0.03)." (PMID 39554503, 2024). "For the study, the enrolled population was divided according to the sarcopenia diagnosis: no sarcopenic patients had higher transferrin (p = 0.03), total proteins (p = 0.04), and azotemia pre-dialysis (p = 0.05) values." (PMID 39554503, 2024). "Compared to patients without sarcopenia, those with probable, confirmed and severe sarcopenia were older, had higher comorbidity scores and lower serum phosphate and transferrin values." (PMID 37208625, 2023). "Transferrin, TIBC, and serum iron levels decreased in hospitalized patients with sarcopenia, but serum ferritin levels did not." (PMID 38719903, 2024).
Thrombocytopenia (8 papers, 2004 to 2025). A reduction in the number of circulating thrombocytes. "Her hemoglobin level was 12.8 g/dL, platelets 113,000/mm3, transferrin saturation 21%, and serum ferritin 23 ng/mL; marrow examination performed to evaluate thrombocytopenia revealed normal cellular morphology and normal iron stores." (PMID 15610558, 2004). "However, some parameters have been reported as a common finding in cases with worse prognosis (i.e., thrombocytopenia or higher CRP, D-dimer, transferrin, and LDH levels, among others)." (PMID 37623875, 2023).
venous thromboembolism (8 papers, 2018 to 2025). Occlusion of the lumen of a vein by a thrombus that has migrated from a distal site via the blood stream. "For instance, elevated levels of TF-positive MPs have been associated with an increased risk of venous thromboembolism in multiple malignancies." (PMID 40312345, 2025). "Possibly the most studied potential biomarker is the coagulation potential of EVs exposing tissue factor (TF+ EV) in cancer patients, to evaluate the relative risk on developing venous thromboembolism (VTE) which is a complication in many cancer patients." (PMID 30186839, 2018). "TF has been linked to venous thromboembolism and poor prognosis in PC patients." (PMID 37386391, 2023). "TF expression in tumor cells is the result of well-defined upstream events that occur during the process of oncogenic transformation, being an important risk factor associated with venous thromboembolism." (PMID 30093972, 2018). "TF binds to circulating coagulation factor VIIa (FVIIa) to form a TF and FVIIa catalytic complex, initiating the extrinsic coagulation pathway and resulting rapid and profound coagulation, often associated with pathological events, such as venous thromboembolism." (PMID 39105809, 2024). "It is believed that TF(+) MPs is involved in the pathogenesis of venous thromboembolism in these patients." (PMID 29991970, 2018). "In the pathogenesis of venous thromboembolism in patients with inflammatory bowel disease, the increased number of circulating TF(+) MPs (procoagulant microparticles) was postulated as an important factor of observed hemostatic abnormalities." (PMID 29991970, 2018). "The TF+ EV activity was measured in patients with various types of advanced cancer, and correlated with the development of venous thromboembolism (VTE)." (PMID 30186839, 2018).
viral hepatitis (8 papers, 2007 to 2023). An acute or chronic inflammation of the liver parenchyma caused by viruses. "A higher ferritin level, transferrin saturation and the number of patients with positive serology for viral hepatitis were also observed in the Tx group." (PMID 31978190, 2020). "Compared to the nTx, the Tx group had a lower BMI, a higher number of patients with positive serology for viral hepatitis (3 with hepatitis B, 3 with hepatitis C and 1 with both), lower concentrations of potassium and albumin and higher levels of ferritin and transferrin saturation." (PMID 31978190, 2020). "Data from 13,006 participants aged 18 to 74 years in the Hispanic Community Health Study/Study of Latinos (HCHS/SOL) without viral hepatitis, excessive alcohol consumption, or high transferrin saturation levels were analyzed." (PMID 34493216, 2021).
aceruloplasminemia (7 papers, 2012 to 2024). An adult-onset disorder of neurodegeneration with brain iron accumulation (NBIA) characterized by anemia, retinal degeneration, diabetes and various neurological symptoms. "As a result, in hereditary aceruloplasminemia patients have low levels of plasma iron and of transferrin saturation with systemic iron excess." (PMID 39628766, 2024). "Aceruloplasminemia patients exhibit low transferrin saturation and tend to develop mild microcytic anemia." (PMID 30420953, 2018).
Cerebral ischemia (7 papers, 2022 to 2025). Restriction of arterial blood supply to the brain associated with insufficient oxygenation to support the metabolic requirements of the tissue. "The expression of transferrin, ferritin and transferrin receptor in the brain is upregulated under condition of cerebral ischemia and hypoxia." (PMID 39042604, 2024). "During cerebral ischemia, large amounts of iron are released from transferrin, inducing iron, transferrin and transferrin receptor (TFR) accumulates intracellularly." (PMID 36210857, 2022). "It was demonstrated that the acidic environment in brain tissue after cerebral ischemia can inhibit the pH-dependent affinity of TF for iron, resulting in final intracellular iron accumulation." (PMID 35637215, 2022). "Additionally, delivery of ASOs conjugated to anti-transferrin antibody has been used to image gene expression in rat models of brain ischemia and brain glial tumors." (PMID 36346674, 2022). "The acidic environment during cerebral ischemia and hypoxia can induce the expression of DMT1 while inhibiting the binding of iron to transferrin, resulting in dissociation between iron and transferrin, thereby increasing brain iron content." (PMID 39042604, 2024). "During cerebral ischemia, the BBB integrity is compromised, allowing iron-free forms (not bound to transferrin) to enter the brain." (PMID 41471697, 2025).
diabetic ketoacidosis (7 papers, 2012 to 2025). The metabolic condition resulted from uncontrolled diabetes mellitus, in which the shift of acid-base status of the body toward the acid side because of loss of base or retention of acids other than carbonic acid is accompanied by the accumulation of ketone bodies in body tissues and fluids. "Mucor requires free iron, and diabetic ketoacidosis leads to partial dissociation of iron bound to transferrin." (PMID 41492613, 2025). "Diabetic ketoacidosis creates low pH environments and elevates free, unbound iron levels through their release from transferrin." (PMID 38786660, 2024). "Protons in diabetic ketoacidosis stimulate a transferrin-mediated displacement of iron." (PMID 38699084, 2024). "Pathogenic mechanisms in aggressive MCM involve reduced phagocytic activity, attainable quantities of ferritin attributed to the displacement of protons by transferrin in diabetic ketoacidosis, and fungal heme oxygenase, which enhances iron absorption for its metabolism." (PMID 36045713, 2022). "Pathogenic mechanisms in the aggressiveness of MCM infection involves the reduction of phagocytic activity, attainable quantities of ferritin attributed with transferrin in diabetic ketoacidosis, and fungal heme oxygenase, which enhances iron absorption for its metabolism." (PMID 36045713, 2022). "In addition to this, the acidic environment that accompanies diabetic ketoacidosis reduces the binding of iron to transferrin, increasing free iron concentration that promotes fungal multiplication." (PMID 33409023, 2020).
end-stage renal disease (7 papers, 2010 to 2024). "Interestingly, one study that compared hemodialysis patients with versus without CVD found that higher transferrin iron binding capacity was associated with increased CVD and end stage renal failure risk." (PMID 35538408, 2022).
Hypoalbuminemia (7 papers, 2013 to 2025). The concentration of albumin in the blood circulation is below the lower limit of normal. "According to the results of this study, hypoalbuminemia and low transferrin levels should be considered dangerous and problematic conditions on their own, especially in nursing home residents." (PMID 37892441, 2023). "Transferrin depletion also affected more patients than hypoalbuminemia or elevated CRP levels." (PMID 28866982, 2017).
nephrotic syndrome (7 papers, 2014 to 2024). A collection of symptoms that include severe edema, proteinuria, and hypoalbuminemia; it is indicative of renal dysfunction. "Increased urinary transferrin excretion has been observed in nephrotic syndrome." (PMID 24790760, 2014). "Excessive urinary losses of iron, TF, EPO, transcobalamin, and some metals were found in patients with nephrotic syndrome." (PMID 36855344, 2023).
neuroblastoma (7 papers, 2006 to 2025). Neuroblastoma (NB) is the most common solid, extracranial childhood tumor. "In vitro studies based on Neuro-2a cells, a mouse neuroblastoma cell line sharing multiple properties with neurons, have indicated that transferrin has a beneficial impact on the cell cycle as it decreases apoptosis and, therefore, promotes neuron survival." (PMID 41225971, 2025). "As expected, the levels of MOR-1 in undifferentiated SH-SY5Y neuroblastoma cell lysates (positive control) were much higher than those observed in TF-1 lysates." (PMID 25338959, 2014). "A similar induction of Pink1 and Prkn, accompanied by increased autophago-lysosomal degradation of mitochondria, was also reported in human neuroblastoma cells upon deprivation from fetal calf serum, which contains transferrin as the key supplier of iron during cell culture." (PMID 33023155, 2020).
retinal degeneration (7 papers, 2010 to 2024). Degeneration of the retina. "Research revealed that in rd10 mice, elevated levels of transferrin and transferrin receptors were accompanied by elevated levels of ferritin and ferritin-bound iron, indicating that retinal degeneration may be linked to altered iron homeostasis." (PMID 38858683, 2024). "Intraocular administration of TF is neuroprotective in various models of retinal degeneration, preventing iron overload and reducing iron-induced oxidative stress." (PMID 36361544, 2022). "We investigated the iron concentration and the protective role of human transferrin (hTf) in rd10 mice, a model of retinal degeneration." (PMID 21179240, 2010). "Importantly, TF was highly potent to preserve photoreceptors in animal models of retinal degeneration induced by iron overload, light exposure, inherited genetic mutations, or retinal detachment." (PMID 32882879, 2020). "Here, the efficacy of TF non-viral gene therapy based on the electrotransfection of pEYS611, a plasmid encoding human TF, into the ciliary muscle was evaluated in several rat models of retinal degeneration." (PMID 32882879, 2020). "We previously reported the protective effect of intravitreal injection of recombinant TF in the light-induced retinal damage (LID) rat model, a well-established model of oxidative stress-induced retinal degeneration." (PMID 32882879, 2020).